ADRB3 (adrenoceptor beta 3)
Diseases named in the same sentence as ADRB3 in open-access papers (continued):
Sharing a sentence is not in itself a finding about the gene and the disease.
heart failure (28 papers, 2012 to 2025). Inability of the heart to pump blood at an adequate rate to meet tissue metabolic requirements. "Using an animal model with transverse aortic constriction (TAC), the authors observed that enhanced expression of RIG-I mediated the protective role of ADRB3 depletion in cardiac hypertrophy and heart failure." (PMID 35693778, 2022). "However, in a pressure overload-induced cardiac hypertrophy and heart failure model, the RIG-I signaling pathway mediated the protective role of ADRB3 depletion by enhancing the innate immune response in the heart." (PMID 35693778, 2022).
Insulin resistance (20 papers, 2004 to 2026). Increased resistance towards insulin, that is, diminished effectiveness of insulin in reducing blood glucose levels. "The transcription factor GLI-similar 3 (GLIS3) rs7034200C/A and adrenergic receptor beta 3 (ADRB3) rs4994T/C (Trp64Arg) polymorphisms are closely related to glucolipid metabolism, insulin resistance, obesity, and increased risk of type 2 diabetes." (PMID 41272565, 2025). "The ADRB3 rs4994T/C (Trp64Arg) SNP, a missense variant, has a C allele that has been linked to lower resting metabolic rates, insulin resistance, and elevated risk of overweight/obesity and T2D." (PMID 41272565, 2025). "ADRB3 is another gene linked to T2D and coronary heart disease wherein ADRB3 polymorphism (Trp64Arg) is associated with central obesity, dyslipidemia, and insulin resistance, all of which are known risk factors for CHD." (PMID 35055468, 2022). "The rs4994 (Trp64Arg) polymorphism of the ADRB3 gene has shown a tendency to have a low resting metabolic rate, abdominal obesity, insulin resistance, and the development of T2D." (PMID 34539437, 2021). "The results obtained suggested that the Trp64Arg polymorphism of ADRB3 was associated with hypertension and insulin resistance." (PMID 34347822, 2021). "In conclusion, the Trp64Arg polymorphism of ADRB3 was associated with hypertension and insulin resistance in a Japanese population." (PMID 34347822, 2021). "The findings of the current study suggest that the ADRB3 C/C genotype is associated with not only an increased BMI and insulin resistance but also the risk of developing NAFLD indirectly." (PMID 31929840, 2019). "Therefore, the Trp64Arg polymorphism of ADRB3 was associated with hypertension and insulin resistance in a healthy Japanese population." (PMID 34347822, 2021). "Due to the relatively weak contribution of the ADRB3 polymorphism to insulin resistance and hypertension, the sample sizes of previous studies may have been insufficient." (PMID 34347822, 2021). "However, the association of the ADRB3 rs4994 (i.e., Trp64Arg) polymorphism with overweight as well as insulin resistance is controversial and likely dependent on ethnicity." (PMID 31929840, 2019). "The ADRB3 rs4994 polymorphism has also been reported to be associated with insulin resistance." (PMID 31929840, 2019). "Moreover, the Trp64Arg polymorphism of the ADRB3 gene is associated with the increased body weight and insulin resistance." (PMID 27246401, 2016). "Since DNA methylation was associated with insulin resistance and thermogenic gene regulation and could regulate histone modifications, we analyzed DNA methylation in CpG sites in the A, B, and C regions on the Adrb3 promoter using bisulfite sequencing." (PMID 31387996, 2019). "This is, to the best of our knowledge, the first study to find a possible association between the ADRB3 rs4994 polymorphism and the development of NAFLD through an increase in BMI and insulin resistance." (PMID 31929840, 2019). "Beta-3-adrenergic receptor (ADRB3) plays a key role in the development of visceral obesity and insulin resistance; however, the effect of ADRB3 polymorphisms on the risk of NAFLD remains unclear." (PMID 31929840, 2019). "Dysfunction of ADRB3 gene therefore could lead to insulin resistance and obesity." (PMID 39640497, 2024).
metabolic syndrome (17 papers, 2011 to 2024). A cluster of metabolic risk factors for CARDIOVASCULAR DISEASES and TYPE 2 DIABETES MELLITUS. "Several possible mechanisms can be proposed to explain the relationship between the ADRB3 Trp64Arg variant and dyslipidemia." (PMID 32430022, 2020). "One of these genes is ADRB3, beta-3 adrenergic receptor, which has been associated with dyslipidemia." (PMID 30954083, 2019). "Guay reported that the ADRB3 gene is associated with dyslipidemia; dyslipidemia is characterized by increased blood levels of LDL-C and triglycerides and reduced levels of HDL-C." (PMID 29046732, 2017). "We also studied the association of the ADRB3 Trp64Arg gene polymorphism with the metabolic syndrome (MetS), defined by elevated WC, TG, BP, FPG, and reduced HDL-C." (PMID 21619577, 2011). "The other study looked into the relationship between metabolic syndrome (Met S) and polymorphisms in LXR-α rs12221497 G>A and adrenergic receptor beta-3 (ADRB3) rs4994 T>C in Pakistanis." (PMID 39569292, 2024). "The ADRB3 variant may increase CHD-modifiable risk factors as it correlates with central obesity and dyslipidemia." (PMID 35055468, 2022). "Japanese researchers found ADRB3 polymorphism association with IR, but not with dyslipidemia." (PMID 21992420, 2011).
myocardial infarction (17 papers, 2012 to 2025). Gross necrosis of the myocardium, as a result of interruption of the blood supply to the area, as in coronary thrombosis. "Meanwhile, a forced expression of ADRB3 exacerbated the progression of myocardial infarction in diabetic rats." (PMID 33549119, 2021).
type 2 diabetes (17 papers, 2009 to 2025). "Furthermore, recent meta-analyses showed that the ADRB3 rs4994 polymorphism is significantly associated with the BMI and type 2 diabetes, especially in Asians, including the Japanese." (PMID 31929840, 2019). "This study investigated the association of SNPs ADRB3(rs4994), ABCC8 (rs1799854),FTO (rs8050136) and TCF7L2(rs7901695 and rs12255372) with type 2diabetes in a sample of the Amazonian population." (PMID 39133695, 2024).
Hypertension (12 papers, 2014 to 2025). The presence of chronic increased pressure in the systemic arterial system. "Characteristics of the investigated studies of the association between β3-Adrenergic receptor (ADRB3) gene Trp64Arg polymorphism and essential hypertension (EH)." (PMID 29670643, 2018). "Summary of meta-analysis of association between β3-Adrenergic receptor (ADRB3) gene Trp64Arg polymorphism and essential hypertension (EH)." (PMID 29670643, 2018). "This meta-analysis was implemented to test the association of a missense mutation, Trp64Arg, in β3-adrenoreceptor-encoding gene (ADRB3) with both hypertension risk and blood pressure (BP) changes." (PMID 28404887, 2017). "As a meta-analysis is widely recognized as a useful and reliable method to address this issue, we set out to meta-analyze the association of ADRB3 gene Trp64Arg polymorphism with both hypertension risk and blood pressure changes using existing publications." (PMID 28404887, 2017). "There were 16 publications testing the association of ADRB3 gene Trp64Arg polymorphism with hypertension risk, incorporating 21 individual studies (3750 hypertensive patients and 4225 normotensive controls)." (PMID 28404887, 2017). "Altogether, ADRB3 gene Trp64Arg mutation was significantly associated with an increased predisposition toward hypertension and elevated systolic/diastolic BP in hypertensive patients, suggesting that Trp64Arg is an important hypertension-susceptibility marker." (PMID 28404887, 2017). "Altogether, our findings not only confirmed the susceptible role of ADRB3 gene Trp64Arg polymorphism in the development of hypertension, but also aid in explaining the conflicting patterns of the association seen in prior studies." (PMID 28404887, 2017). "Some clinical studies pointed to a possible relationship between arterial hypertension and W64R polymorphism of the ADRB3 gene as well as to a relationship between this genotype and higher mortality among hypertensive patients." (PMID 25800470, 2015). "The genomic sequence of ADRB3 gene is covered with many polymorphic loci, and a missense mutation, Trp64Arg, in its first exon has been widely evaluated in susceptibility to hypertension and other complications in populations from different regions of the world." (PMID 28404887, 2017). "Since the year 1996, a growing number of epidemiological studies have tested the association of ADRB3 gene Trp64Arg polymorphism with hypertension risk and the changes of relevant intermediate phenotypes, such as blood pressure, body mass index (BMI) and fasting insulin." (PMID 28404887, 2017). "Given the biological importance of β3-adrenoreceptor, it would be tempting to speculate that certain genetic alterations of its coding gene, ADRB3, might play a critical role in the regulation of blood pressure and ultimately predispose to the occurrence of hypertension." (PMID 28404887, 2017). "Hence, the presence of genetic heterogeneity might undermine the replication of association between ADRB3 gene and hypertension." (PMID 28404887, 2017). "We concede that replication of our findings in other well-designed studies with a larger sample size will add additional evidence to our existing knowledge on a contributing role of ADRB3 gene to the etiology of hypertension." (PMID 28404887, 2017). "However, clinically used non-selective Adrb3 agonists have led to off target side-effects such as tachycardia and hypertension, which precludes the use of these Adrb3 agonists as beiging agents in the clinic." (PMID 29019320, 2017).
cardiac hypertrophy (11 papers, 2012 to 2025). "Overall, these findings suggested that miR-18a targeting ADRB3 inhibited cardiomyocyte fibrosis, cardiac hypertrophy and apoptosis." (PMID 33549119, 2021).
breast carcinoma (9 papers, 2008 to 2023). "The Trp64Arg polymorphism in ADRB3 increased the risk of endometrial cancer but was associated with decreased susceptibility for breast cancer." (PMID 36902678, 2023). "ADRB3 loss impedes mammary tumor occurrence through the interplay between viral proteins (PyMT) and nucleolus of mammary epithelial cells in MMTV-PyMT mice." (PMID 35145073, 2022). "In addition, the Trp64Arg polymorphism in ADRB3 (β3-AR gene) was reported to be associated with susceptibility to endometrial cancer and decreased risk for breast cancer, especially when associated to Gln27Glu polymorphism in ADRB2 (β2-AR gene)." (PMID 32983164, 2020). "Collectively, ADRB3 promotes metastasis by inducing mobilization and inhibiting differentiation of both breast cancer cells and MDSCs." (PMID 35145073, 2022). "Immunohistochemistry revealed ADRB3 expression is significantly more frequent in breast cancer tissues than in adjacent noncancerous tissues (92.1% vs. 31.5%)." (PMID 35145073, 2022). "For example, the expression of ADRB3, which mediates catecholamine-induced activation of adenylate cyclase through G proteins, is three times more frequent in breast cancer tissues than in adjacent noncancerous tissues and correlates with the TNM stage and poor prognosis." (PMID 37296983, 2023). "Hence, ADRB3 promotes the expansion of MDSC through BM mobilization and inhibition of immature myeloid cell differentiation and promotes the expansion of ER+ human breast cancer cells." (PMID 37296983, 2023). "Most proteins are moderately to highly expressed in several breast cancer cases with at least one antibody checked, the exception being ADGRA2, ADRB3 and STAR, whose genes are also not over-expressed at the mRNA level." (PMID 32987805, 2020). "Evaluation of the median mRNA expression of genes of the amplicon in TCGA breast cancer study discloses that a few genes (GOT1L1, ADRB3, STAR and LETM2) have a very low or no expression in breast cancers." (PMID 32987805, 2020).
Abdominal obesity (6 papers, 2012 to 2023). Excessive fat around the stomach and abdomen. "Trp64Arg mutation of ADRB3 is associated with lower resting metabolic rate, abdominal obesity, weight gain, and difficulty losing weight." (PMID 22937051, 2012). "Thus, the association found between the risk allele (G) of the rs4994 (ADRB3), the most commonly investigated ADRB3 variant, with abdominal obesity and excess weight among indigenous people corroborates results already described in different populations." (PMID 35560161, 2022). "Despite the low prevalence of nutritional and metabolic alterations in most of the analyzed indigenous groups, a significant association was found between the ADRB3 gene and abdominal obesity and excess weight, and the KCNJ11 gene with hyperglycemia for indigenous people in general." (PMID 35560161, 2022). "In many ethnic groups, the Arg64 allele in ADRB3 is associated with the early onset of abdominal obesity and non-insulin-dependent DM." (PMID 33603663, 2020). "MDA was the variable that was most positively associated with the estimated LDL-C levels in all multivariate models composed of variables associated with LPL, ADRB3 and MTHFR gene methylation levels, oxidative stress, inflammation, abdominal obesity, food intake and epidemiological variables." (PMID 33326437, 2020).
atrial fibrillation (4 papers, 2020 to 2025). A disorder characterized by an electrocardiographic finding of a supraventricular arrhythmia characterized by the replacement of consistent P waves by rapid oscillations or fibrillatory waves that vary in size, shape and timing and are accompanied by an irregular ventricular response. "An existing study reported an overexpression of ADRB3 in canine models of atrial fibrillation, and that ADRB3 up-regulation elevated atrial myocyte apoptosis, fibrosis and atrial dilatation." (PMID 33549119, 2021).
leukemia (4 papers, 2020 to 2024). A malignant (clonal) hematologic disorder, involving hematopoietic stem cells and characterized by the presence of primitive or atypical myeloid or lymphoid cells in the bone marrow and the blood. "Additionally, blocking ADRB3 promoted apoptosis and reduced chemoresistance in leukemia cells." (PMID 38217005, 2024).
angiosarcoma (3 papers, 2013 to 2022). A malignant tumor arising from the endothelial cells of the blood vessels. "Therefore, the purpose of the present research work was to study the mRNA expression levels of the three subtypes of the β-AR genes (ADRB1, ADRB2, ADRB3) in hemangiosarcoma (HSA) and hemangioma (HA), as well as in vascular hamartomas (VH) from dogs." (PMID 35637463, 2022). "To confirm this, we performed immunohistochemistry for the steady state protein levels of ADRB1, ADRB2, and ADRB3 on four clinically characterized human angiosarcoma tumors, revealing strong signals for ADRB1 and ADRB2 and weaker sample-dependent signals for ADRB3." (PMID 23555867, 2013).
Ewing sarcoma (3 papers, 2016 to 2024). A small round cell tumor that lacks morphologic, immunohistochemical, and electron microscopic evidence of neuroectodermal differentiation. "Beta-3-adrenergic receptor (ADRB3) as well as chondromodulin-1 (CHM1) are over-expressed in Ewing Sarcoma (ES) but not on T cells." (PMID 27447745, 2016).
familial hypercholesterolemia (3 papers, 2019 to 2022). An inheritable form of hyperlipidemia, in which there are excess lipids in the blood. "An investigation on 61 familial hypercholesterolemia patients showed higher ADRB3 DNA methylation levels were significantly associated with LDL levels." (PMID 35655232, 2022). "After adjustment with age, blood lipid profile and ADRB3 gene promoter genotype, ADRB3 DNA methylation levels in obese men were lower than familial hypercholesterolemia men." (PMID 35655232, 2022). "Although the population is different from the present study, it has been shown in men with familial hypercholesterolemia (FH) that the mean methylation levels of the ADRB3 gene were lower and correlated with high levels of LDL-C." (PMID 33326437, 2020).
Hyperglycemia (3 papers, 2018 to 2022). An increased concentration of glucose in the blood. "ADRB3-rs4994 and ABCC8-rs1799854 genes showed a significant association with BMI and waist circumference, and the KCNJ11-rs5219 gene with hyperglycemia." (PMID 35560161, 2022).
dyslipidaemias (2 papers, 2018 to 2019). "The results of our investigation have clearly highlighted the strong association with ADRB3 polymorphism, where the mutant Arg allele in ADRB3, significantly associates with a greater body weight and higher BMI, elevated leptin and dyslipidaemias both in heterozygous and homozygous." (PMID 29587766, 2018).
gallstones (2 papers, 2009 to 2013). Solid crystalline precipitates in the biliary tract, usually formed in the gallbladder, resulting in the condition of cholelithiasis. "Our multi-analytic approach revealed that the combination of genotypes of respective polymorphisms as ESR1 IVS1-397 variant, ABCG8 145 variant, ESR1 IVS1-351 variant and ADRB3 190 variant pose a significant risk for developing gallstone." (PMID 23577061, 2013). "Another recent association study observed an Arg64-variant of the β3-adrenergic receptor (ADRB3) more frequently in gallstone patients." (PMID 19823678, 2009). "Furthermore, on subdividing the study groups on the basis of gender we observed that ESR1 IVS1-397C>T and ADRB3 -190 T>C conferred increased risk for gallstones in female gender." (PMID 23577061, 2013).
left ventricular hypertrophy (2 papers, 2011 to 2022). Enlargement of the LEFT VENTRICLE of the heart. "Besides the ADRB3, some genetic variants of the cardiac B 1 adrenoreceptor may play a role in the development of left ventricular hypertrophy in patients after acute coronary event in patients without DM or AH." (PMID 21992420, 2011).
lipid metabolic disorders (2 papers, 2016 to 2021). "Adrb3 has been reported to be associated with lipid metabolism disorders, and its gene expression increases with elevated LDL level and hypertriglyceridemia, but is normal in the lean body." (PMID 34760253, 2021).
lung carcinoma (2 papers, 2014 to 2020). "Finally, we evaluated the association between ADRB3 expression in lung cancers and the impact on patients’ survival." (PMID 32514619, 2020). "We found elevated levels of ADRB3 in lung cancer cells as well as Mo-AMs in the peritumoral region from NSCLC patients." (PMID 32514619, 2020). "We found that pcDNA3-ADRB3 conferred a proliferative advantage to A549 cells suggesting a role of ADRB3 in promoting lung cancer growth." (PMID 32514619, 2020). "We found that lung cancer cells aberrantly express ADRB3 and activation of this receptor promotes tumor cell growth." (PMID 32514619, 2020). "ADRB3 supports lung cancer cells proliferation and promotes chronic inflammation." (PMID 32514619, 2020). "Finally, Anti-ADRB3 monoclonal antibody inhibited the growth of lung cancer in mice." (PMID 32514619, 2020).
sarcoma (2 papers, 2024 to 2025). A usually aggressive malignant neoplasm of the soft tissue or bone. "Similarly, mesenchymal genes with high expression in STS, like MXRA8, could be combined with genes present in normal stromal cells but not in sarcoma cells as ADRB3." (PMID 40814001, 2025).
schizophrenia (2 papers, 2017 to 2025). A major psychotic disorder characterized by abnormalities in the perception or expression of reality. "However, several VMPs exhibited opposite patterns of variance between blood and brain regions, including some within the GRIK3, GFI1, ADRB3 and MND1 genes, amongst others, indicating that some schizophrenia associated VMPs may exhibit divergent variance patterns between the periphery and brain." (PMID 39271751, 2025).